RNU6-787P (RNA, U6 small nuclear 787, pseudogene)
Gene: Small nuclear RNA gene on chromosome 3 (66,293,114 to 66,293,220, reverse strand). Ensembl gene ENSG00000206759.
Homologues: Orthologues: chimpanzee U6 (92% identical), mouse Gm55982 (70% identical). Paralogues in human: RNU6-41P (91% identical), RNU6-12P (90% identical), RNU6-13P (90% identical), RNU6-25P (90% identical), RNU6-32P (90% identical), RNU6-33P (90% identical), RNU6-36P (90% identical), RNU6-842P (90% identical), RNU6-1 (89% identical), RNU6-1011P (89% identical), RNU6-17P (89% identical), RNU6-18P (89% identical), and 1288 more.